FKBP2 (FKBP prolyl isomerase 2)
Description:
PPIases accelerate the folding of proteins. It catalyzes the cis-trans isomerization of proline imidic peptide bonds in oligopeptides.
Synonyms: FKBP-13; FKBP13; PPIase
Tractability: Small molecule: a structure with a bound ligand is known; it belongs to a druggable protein family. Antibody: UniProt places it where antibodies can reach, with high confidence; UniProt predicts a signal peptide or a membrane-spanning region; the Human Protein Atlas places it where antibodies can reach. PROTAC: its protein half-life has been measured; a small molecule that binds it is known.
Target class: Isomerase; Enzyme
Gene: Protein-coding gene on chromosome 11 (64,241,003 to 64,244,132, forward strand). Ensembl gene ENSG00000173486.
Subcellular location: Endoplasmic reticulum membrane
Subcellular location (Human Protein Atlas): Plasma membrane
Gene Ontology:
Molecular function: protein binding; FK506 binding; peptidyl-prolyl cis-trans isomerase activity
Cellular component: endoplasmic reticulum; endoplasmic reticulum membrane
Genetic constraint (gnomAD): Loss-of-function variants: 15 observed, 18.95 expected, observed/expected ratio (o/e) 0.79, 90% interval 0.53 to 1.22. The upper end of that interval is the gene's LOEUF score, 1.22, which puts it in group 5 of 6, group 1 being the genes least tolerant of losing a copy. Missense variants: 170 observed, 170.67 expected, observed/expected ratio (o/e) 1, 90% interval 0.88 to 1.13. Synonymous variants: 76 observed, 71.01 expected, observed/expected ratio (o/e) 1.07, 90% interval 0.89 to 1.29.
Homologues: Orthologues: chimpanzee FKBP2 (99% identical), macaque FKBP2 (99% identical), dog FKBP2 (96% identical), guinea pig FKBP2 (96% identical), pig FKBP2 (96% identical), rat Fkbp2 (96% identical), mouse Fkbp2 (95% identical), zebrafish fkbp2 (78% identical), tropical clawed frog fkbp2 (73% identical), Caenorhabditis elegans fkb-1 (61% identical), rabbit FKBP2 (61% identical), Drosophila melanogaster CG14715 (54% identical). Paralogues in human: FKBP9 (39% identical), FKBP11 (39% identical), FKBP10 (38% identical), FKBP14 (35% identical), FKBP3 (35% identical), FKBP1A (34% identical), FKBP1C (33% identical), FKBP5 (33% identical), FKBP7 (32% identical), FKBP4 (31% identical), FKBP1B (30% identical), FKBP15 (27% identical), and 6 more.
Diseases named in the same sentence as FKBP2 in open-access papers:
FKBP2 is named in the same sentence as 22 diseases in open-access papers, as found by Europe PMC text mining. Sharing a sentence is not in itself a finding about the gene and the disease. The quoted sentences say what the papers report.
lung fibrosis (2 papers, 2022 to 2023). "FKBP2 was enriched in fibrotic regions in IPF lungs, while, in the bleomycin-induced mouse model of lung fibrosis, deficiency of FKBP2 aggravated fibrogenesis and impaired resolution of fibrosis." (PMID 35456020, 2022).
Type 2 Diabetes (2 papers, 2017 to 2023). "The FKBP2 gene has been associated with pathological osteoporosis, and its protein product was suggested to be associated with the development of type 2 diabetes." (PMID 28152021, 2017).
autoimmune disease (1 paper, 2022). A disorder resulting from loss of function or tissue destruction of an organ or multiple organs, arising from humoral or cellular immune responses of the individual to their own tissue constituents. "While FKBP10, FKBP11 (this study), and FKBP2 have been reported in the context of IPF, others have demonstrated a role of FKBP11 in autoimmune disease." (PMID 35456020, 2022).
breast carcinoma (1 paper, 2013). "FKBP2 appears to play a role in breast cancer and treatment with estradiol led to a 14-fold increase in expression." (PMID 24278769, 2013). "It had been shown previously that Cyp40 and FKBP2 are increased in mammary carcinoma cells by estradiol and that the antiestrogen drug ICI 182, 780 antagonized these increases." (PMID 24278769, 2013).
glaucoma (1 paper, 2023). Increased pressure in the eyeball due to obstruction of the outflow of aqueous humor. "This study identified IL18, TLR9, NFKB1, HDAC4, FKBP2, and KITLG as hub genes in glaucoma that are gut microbiota-related as well as showed that the regulation of immune response by gut microbiota is associated with glaucoma." (PMID 37605653, 2023).
leukopenia (1 paper, 2018). "Individually, analysis of secondary outcomes revealed that FKBP2 c.-2110GG genotype carriers had higher risk of leukopenia, FKBP1A n.259+24936C allele carriers had increased risk of constipation, and FOXP3 c.-22-902A or c.-23+2882A allele had higher risk of gastrointestinal disorders (p < 0.05)." (PMID 30487748, 2018). "Multivariable regression analysis showed that FKBP2 c.-2110GG genotype did not remained associated with leukopenia using the model 1 (adjusted p = 0.085)." (PMID 30487748, 2018). "FKBP2 c.-2110GG genotype (OR = 3.87, 95% CI = 1.26–11.91, p = 0.018), therapy group (TAC+MPS; OR = 3.66, 95% CI = 1.19–11.28, p = 0.024) and CMV (OR = 9.68, 95% CI = 3.08–30.38, p = 0.0001) were associated with leukopenia (p < 0.05)." (PMID 30487748, 2018). "Moreover, FKBP2 c.-2110G>T was associated with adverse event (leukopenia) but not with renal dysfunction or acute rejection in this sample population." (PMID 30487748, 2018). "This might imply that CMV treatment is a strong predictor for leukopenia events rather than the FKBP2 c.-2110G>T variant." (PMID 30487748, 2018).
lung carcinoma (1 paper, 2009). "Associated with lung cancer are FK506 binding protein 2 (FKBP2) and Plunc (palate, lung and nasal epithelium carcinoma associated)." (PMID 19347046, 2009).
melanoma (1 paper, 2022). A malignant, usually aggressive tumor composed of atypical, neoplastic melanocytes. "Applying SLF′-thalidomide to FKBP2-tagged KDM5B in WM3734 melanoma cells, we could demonstrate that KDM5B protein is quickly proteosomally degraded in an E3 ubiquitin ligase-dependent manner." (PMID 35650266, 2022).
multiple endocrine neoplasia type 1 (1 paper, 2017). An autosomal dominant tumor predisposition syndrome caused by pathogenic variants in the MEN1 gene, characterized by an increased risk of tumors of the parathyroid glands, pituitary gland, and foregut neuroendocrine tumors (most commonly pancreatic islet cells). "Northern blotting revealed that FKBP2 is expressed in tissues that are predisposed to hyperplasia in multiple endocrine neoplasia type 1 (MEN1) patients; however, mutation analysis of MEN1 kindreds and sporadic tumors excluded FKBP2 as a candidate gene for MEN1." (PMID 28152021, 2017).
myeloma (1 paper, 2023). "Other FKBPs with relevant affinities to FK506 are FKBP13 (FKBP2) (Ki = 302 nM), FKBP51 (FKBP5) (Ki = 406 nM) and FKBP52 (FKBP4) (Ki = 56 nM), all of which are expressed in myeloma cell lines." (PMID 36717825, 2023).
cancer (9 papers, 2009 to 2024). A tumor composed of atypical neoplastic, often pleomorphic cells that invade other tissues. "Interestingly, 46 molecules in the network of the calgranulin B-interacting proteins are known to be associated with cancer and FKBP2 was found to interact with calgranulin B in both SNU-484 and SNU-81 cells." (PMID 28152021, 2017). "All candidate molecules interacting with calgranulin B were unique in three cell lines except FKBP2 that was found in two cancer cell lines, SNU-484 and SNU-81." (PMID 28152021, 2017). "In contrast, the expression levels of TXNDC5, CD38, GAS6, FKBP2 and SDC1 were increased in the late stage of LUAD progression, indicating potential distinct roles in the occurrence and progression of the cancer." (PMID 37728413, 2023). "Among the calgranulin B-interacting molecules known to be involved in cancer (purple), FKBP2 (FK506-binding protein 2) was identified from both SNU-484 and SNU-81 cells." (PMID 28152021, 2017). "Our DGE analysis of non-responding gene expression areas provides some initial molecular detail and shows an upregulation of genes involved in migration, resistance, immunosuppressive function, inflammation, cancer, and tumor stroma (e.g., H2AFJ, FKBP2, MGP, A2M, and IGFBP7)." (PMID 36115838, 2022).
tumor (4 papers, 2021 to 2024). "The top genes in cold tumor are ARF1, PDIA3, ALDOA, FKBP2, NDUFS5, NDUFC1, COX7A2, C14orf2, LNX1, and BTBD6." (PMID 33816503, 2021).
infection (1 paper, 2023). The state of being infected such as from the introduction of a foreign agent such as serum, vaccine, antigenic substance or organism. "In addition, the analysis revealed that some of these proteins had been previously associated to SARS-CoV-2 early (FKBP2; UBXN1; PPP1R11), middle (UBXN1; PPP1R11; CAPN5) and late-stage infection in human male blood (FKBP2; UBXN1; PPP1R11; SURF4; SSU72)." (PMID 37063416, 2023).
FKBP2 also shares sentences with these, for which no sentence is quoted: colorectal cancer (1 paper); gastrointestinal disorders (1); idiopathic pulmonary fibrosis (1); leukemia (1); lupus (1); lymphoma (1); osteoporosis (1); plasmacytoma (1); renal dysfunction (1).